INS (insulin)
Diseases named in the same sentence as INS in open-access papers (continued):
Sharing a sentence is not in itself a finding about the gene and the disease.
Obesity (continued). "Associations between obesity and cancer risk are explained with different suggestions, such as increased synthesis of bioavailable growth factors, insulin, and IGF-1 due to IR, synthesis of sex hormones, and chronic local inflammation." (PMID 38392069, 2024). "Obesity is a global epidemic disease and a risk factor for heart metabolic complications, such as insulin sensitivity, type 2 diabetes, and non-alcoholic fatty liver disease." (PMID 39644184, 2024). "Obesity is associated with increased glucose levels (hyperglycemia) and elevated fasting and non‐fasting insulin levels (hyperinsulinemia)." (PMID 39466902, 2024). "Fasting total GLP-1 was positively associated with overweight and obesity in theprediabetes cohort, even when adjusted for glycemic status or insulin sensitivity andliver fat." (PMID 38686701, 2024). "Potential underlying factors of disease associated with obesity involve disturbances in inflammatory and insulin signaling, which impair glucose homeostasis." (PMID 38886475, 2024). "Multivariable regression analysis was performed to assess potential risk factors associated with elevated glucose, insulin, and C-peptide levels at 0h in individuals with obesity." (PMID 39439559, 2024). "Researchers should continue to use glucose/insulin biomarkers and lipid biomarkers in intervention studies due to their close association with obesity and T2DM." (PMID 39519417, 2024). "Several positive associations have been reported between the intake of processed red meats and increased blood glucose concentrations, insulin levels, and risk for obesity." (PMID 38257161, 2024). "In humans, obesity is known to be associated with nonalcoholic fatty liver disease, where the accumulation of triglycerides in the liver correlates with insulin resistance in various tissues, including the liver, muscle, and adipose tissue." (PMID 39684905, 2024). "Nevertheless, regular physical activity and long-term weight loss are still recommended for individuals with obesity, as research has confirmed that successful weight loss maintainers proved sustained improvements in insulin sensitivity." (PMID 38297286, 2024). "Elevated insulin levels can promote weight gain and increase the risk of obesity, which, in turn, can disrupt circadian rhythms and sleep cycles." (PMID 39201889, 2024). "Sarcopenia and obesity exacerbate each other, as muscle loss decreases the amount of insulin-responsive tissue, leading to insulin resistance, which further heightens anabolic resistance." (PMID 39727928, 2024). "Obesity has been associated with altered levels of insulin, insulin-like growth factor-1, steroid hormones, cytokines, leptin, and adiponectin." (PMID 39335119, 2024). "Ludwig Ludwig DS DS Carbohydrate-insulin model: does the conventional view of obesity reverse cause and effect?" (PMID 38884643, 2024). "Interventions combining HIIT and RT have been shown to induce superior benefits than endurance or RT alone in inducing weight-loss and improving glycemic control, insulin sensitivity and cardio-vascular risk among patients with T2D with overweight/obesity." (PMID 39633643, 2024). "Genes assigned by MRS were functionally associated with insulin secretion, beta-cell function, obesity, and aging." (PMID 39511564, 2024). "A significant body of research demonstrated a strong correlation between transaminase levels and MASLD risk factors, including obesity, dyslipidemia, and elevated insulin levels." (PMID 39703225, 2024). "UCP1 expression in BAT, but not in WAT or brown/white differentiated pre-adipocytes, was reduced with increasing age, obesity, and adverse cardiometabolic risk factors such as fasting glucose, insulin, and blood pressure." (PMID 38917410, 2024). "Obesity is associated with hypertension, and the mechanism has tought to be related to reduced nitric oxide-mediated dilation, along with impaired thalamic insulin signaling, K+ channel function and sympathetic function." (PMID 38553569, 2024).
Obesity (continued). "The possible underlying mechanisms can be related to desensitization of insulin signalling in brains (i.e. attributed to obesity and T2DM), impaired insulin function in the CNS, and attenuated sensitivity of insulin receptors." (PMID 38441832, 2024). "Given that obesity and unbalanced dietary composition cause more disruption in insulin metabolism and inflammation, we therefore adjusted for BMI and energy difference and other relevant factors such as age and physical activity." (PMID 39618714, 2024). "Human adenovirus-36 (HAdV-36) infection has been linked to obesity, low lipid levels, and improvements in blood glucose levels and insulin sensitivity in animal models and humans, although epidemiological studies remain controversial." (PMID 38932214, 2024). "Linear regression was used to assess associations between proteomics and obesity groups as well as cardiometabolic traits of glucose, insulin, and lipid profiles at baseline and follow-up visits." (PMID 38548792, 2024). "Obesity is caused by the body’s impaired glucose and lipid metabolism, with insulin action primarily targeting hepatocytes and adipocytes." (PMID 38674532, 2024). "The mechanism underlying HTN secondary to obesity is complex and mainly involves sympathetic nervous system activation, increased mineralocorticoid activity, sodium reabsorption, and insulin resistance." (PMID 38172674, 2024). "Obesity can also affect fertility through abnormalities in lipid metabolism and insulin metabolism, and is an independent risk factor for female infertility." (PMID 38348417, 2024). "Iron deficiency can also impair insulin expression and lead to metabolic changes through association with obesity." (PMID 38840960, 2024). "They encompass aspects of body mass, cardiovascular health, metabolic health, and insulin metabolism, collectively providing valuable insight into the health status and associated risks of children and adolescents with overweight/obesity." (PMID 39185113, 2024). "The miR-143/miR-145 cluster has an essential role in intestinal epithelium regeneration by modulating the insulin growth factor signaling pathway, and it is also implicated in obesity." (PMID 38791975, 2024). "Higher glucose levels in individuals with obesity are often caused by decreased insulin sensitivity." (PMID 38664368, 2024). "CD40L deficiency in mice attenuates obesity-linked AT inflammation and hepatic steatosis and increases systemic insulin sensitivity." (PMID 38455510, 2024). "Obesity is associated with adipose tissue macrophage infiltration promoting chronic low-grade inflammation, contributing to impaired insulin sensitivity and energy expenditure processes." (PMID 38302438, 2024). "It has been demonstrated that obesity-induced inflammation in the hypothalamus causes cellular resistance to insulin and leptin, resulting in problems of the hypothalamus’ function to regulate the homeostatic appetite system." (PMID 39266589, 2024). "In cancer, insulin signaling is a major factor linking obesity to cancer progression and has been implicated in resistance to chemotherapy." (PMID 39622796, 2024). "Duclos's study suggests that both obesity and DM increase OA risk through mechanical and metabolic pathways, including adipokine production and insulin resistance." (PMID 39664154, 2024). "A causal role of hyperinsulinemia in obesity is further supported by the observation that a pharmacological reduction in insulin secretion lowers body weight in people who are obese." (PMID 38791525, 2024). "Accordingly, mice generated by the deletion of one of the insulin alleles resulting in lower diet-induced insulin levels were resistant to diet-induced obesity and showed increased browning of WAT." (PMID 39594650, 2024). "Excess insulin secretion has been associated with oxidative stress and accelerates beta-cell dysfunction in humans, increasing the risk of type 2 diabetes and obesity." (PMID 39716153, 2024).
Obesity (continued). "FO is known to reduce body weight, triglycerides, and obesity risk at the molecular level due to its protective effects on pro-inflammatory markers and insulin sensitivity." (PMID 38672435, 2024). "Cer is well known to accumulate during obesity, with decreased Cer levels being associated with increase in insulin sensitivity in mice and humans." (PMID 39297163, 2024). "Common risk factors include obesity, family history, shared pathological changes such as reduced insulin sensitivity and insufficient insulin secretion, and common clinical manifestations like polydipsia, polyuria, increased appetite, and fatigue." (PMID 38962677, 2024). "As with healthy volunteers, infusion of glucagon in patients with overweight/obesity is associated with an increase in plasma insulin and glucose." (PMID 38579751, 2024). "Although copper is essential for the breakdown of fat cells, high blood copper levels are associated with obesity, and serum copper levels are positively correlated with BMI, leptin, and insulin." (PMID 37132140, 2024). "The elevated insulin levels associated with obesity correspond with decreased levels of the Sex Hormone Binding Globulin (SHBG) in men." (PMID 38892561, 2024). "In summary, obesity was associated with insulin dysregulation, oxidative stress, and decreased mitochondrial function in mares." (PMID 38886475, 2024). "Adipocyte differentiation, lipid metabolism, insulin sensitivity, oxidative capability, and thermogenesis are all negatively impacted by obesity-associated mitochondrial dysfunction, which ultimately leads to metabolic disorders." (PMID 38928386, 2024). "With accumulating evidence for the association of increased fasting GLP-1 withprediabetes, obesity, and insulin sensitivity, further research is needed to uncover theunderlying mechanism to understand the relevance of this association." (PMID 38686701, 2024). "Women with a surplus of visceral adipose tissue also have increased ovarian androgen production, likely caused by elevated insulin levels that often occur with obesity." (PMID 38172476, 2024). "T2D has previously been regarded as a metabolic condition associated with BMI obesity that results in faulty insulin sensitivity and decreased glucose uptake." (PMID 38613048, 2024). "Since CARTp-deficient mice exhibit late-onset obesity and impaired insulin secretion, these findings were confirmed." (PMID 38577975, 2024). "MASLD emerges as a complex, multifaceted condition intricately linked to various factors, including oxidative stress, insulin resistance, lipid abnormalities, metabolic dysregulation, obesity, immune modulation, and alterations in the gut microbiota." (PMID 38732118, 2024). "Impaired insulin sensitivity, abnormal insulin production from pancreatic β-cell dysfunction, uncontrolled glucagon release, hypertriglyceridemia, and obesity all contribute to the risk for NODAT." (PMID 38610694, 2024). "Obesity is a persistent medical condition with a multifaceted origin, linked to disrupted lipid and glucose metabolism, diminished insulin sensitivity, abnormal inflammatory reactions, and reduced antioxidant capability." (PMID 39458556, 2024). "Late mealtimes, which often result from circadian misalignment, have also been linked to weight gain and obesity, with potential underlying mechanisms including decreased energy expenditure during rest and after eating and increased insulin resistance." (PMID 38838328, 2024). "Obesity in mares was significantly associated with insulin dysregulation, reduced muscle mitochondrial function, and decreased skeletal muscle oxidative capacity with greater ROS production when compared to NW." (PMID 38886475, 2024). "On the other side, obesity causes increased oxidative stress, systemic inflammation, insulin resistance and bone marrow adiposity." (PMID 39300501, 2024). "In fast eaters, insulin secretion is less in the first minutes and at the end of the meal, which increases the risk of obesity." (PMID 39015536, 2024).
Obesity (continued). "In the treatment study, oral administration of SFN (40 mg/kg) induced weight loss and improved insulin sensitivity and plasma lipid profile in the diet-induced-obesity (DIO) male mice." (PMID 38611359, 2024). "Persistently high circulating insulin levels (hyperinsulinemia) are usually associated with obesity and T2DM." (PMID 39062179, 2024). "In men with overweight and obesity, weight loss primarily acts by reducing adipose tissue, inflammation, and improving insulin sensitivity, leading to increased testosterone production." (PMID 38892561, 2024). "Obesity, especially intra-abdominal adiposity, is known to be linked to issues in glucose metabolism and insulin resistance." (PMID 39852345, 2024). "Obesity causes fat accumulation, and sarcopenia causes loss of muscle mass and strength; together, they worsen insulin resistance and accelerate muscle decline, creating a harmful cycle." (PMID 39727928, 2024). "The decreased serum MaR1 concentration tightly associated with obesity, impaired glucose and lipid metabolism, reduced first‐phase of glucose‐stimulated insulin secretion, and enhanced insulin resistance." (PMID 38463394, 2024). "Excitingly, plasma concentrations of SHBG were shown to be associated with insulin concentrations and obesity." (PMID 38725482, 2024). "Rodents that are genetically predisposed to obesity and those subjected to a high-fat diet demonstrated hepatic insulin resistance alongside increased hepatic diacylglycerol (DAG) levels." (PMID 39807459, 2024). "This cascade of events disrupts metabolic regulation and impairs insulin sensitivity, predisposing children to obesity." (PMID 39346600, 2024). "Increased ROS levels in obesity are associated with adipogenic BMSCs that demonstrate a shift from glycolysis towards higher oxidative phosphorylation, enhanced insulin signaling, glucose transport, lipid metabolism, and senescence." (PMID 39188529, 2024). "The ADIPOQ gene encodes adiponectin, an adipokine secreted by adipocytes that plays a crucial role in regulating various cellular processes associated with obesity, including lipid metabolism and insulin sensitivity." (PMID 38612576, 2024). "Overall, obesity-associated endocrine deregulation marked by alterations in adiponectin, leptin, insulin, IGF1 and estrogens contributes to increased risk of cancer progression and recurrence in obese breast cancer patients." (PMID 39253073, 2024). "Obesity is linked to IR and higher insulin levels, which can lead to the increased production of ovarian androgens." (PMID 38613082, 2024). "Obesity is associated with increased plasma insulin concentrations both at baseline and postprandially." (PMID 38942960, 2024). "FMT is associated with mixed results in obesity management, with some promising effects, especially in improving insulin sensitivity, but with limited impact on weight loss." (PMID 39338443, 2024). "In a previous study we found higher fasting glucagon in individuals with obesity compared to controls with normal weight to be significantly associated with higher insulin, free fatty acids, triglycerides and visceral adipose tissue (VAT)." (PMID 39027470, 2024). "Lipid accumulation in tissues, particularly in muscles and the liver, disrupts insulin signalling, reduces cellular sensitivity to insulin, and perpetuates a cycle of worsening IR and metabolic disturbances associated with obesity." (PMID 39876920, 2024). "In adult cohorts, it has been reported that IL-36γ is elevated in obesity and correlates with improved metabolic health, whereas in childhood cohorts, IL-36β is the family member associated with insulin sensitivity." (PMID 38467728, 2024). "The increase in fat depots in obesity, particularly visceral adipose tissue, associates with macrophage-induced inflammation, which perturbs insulin sensitivity." (PMID 38845049, 2024).
Obesity (continued). "LncRNA also play an important role in obesity, regarding energy expenditure, appetite regulation, insulin sensitivity and other obesity-associated inflammatory conditions." (PMID 38605957, 2024). "Some studies have indicated that in WAT, renin-angiotensin system activation has a significant impact on insulin sensitivity and inflammation and plays an important role in the progression of metabolic disorders associated with obesity." (PMID 39000187, 2024). "Obesity is frequently associated with higher circulating insulin levels, which stimulates ovarian androgen production, as well as peripheral aromatization of androgens to estrogens." (PMID 38765954, 2024). "Longer sleep duration and time spent in bed on weekends and weekdays were significantly associated with better insulin sensitivity in adolescents with obesity." (PMID 39192029, 2024). "Using the 2-deoxy-2-18F-fluoro-D-glucose ([18F]FDG) positron emission tomography (PET) method, insulin-stimulated brain glucose uptake (GU) has been shown to be increased in obesity and associate negatively with whole-body insulin sensitivity." (PMID 38651416, 2024). "Obesity-associated inflammation contributes to insulin signaling impairment through numerous circulating cytokines and also by directly impacting cytokine-producing organs, such as the liver and muscle tissue." (PMID 39684547, 2024). "elucidate obesity’s pivotal role in breast cancer (BC) risk, particularly postmenopausal women, citing hormonal imbalances and insulin resistance among its mechanisms." (PMID 38699635, 2024). "KEGG pathway analysis of RNAseq results showed that NP627 affected genes in the AMPK-signaling, PI3K-AKT-signaling, and insulin-signaling pathways, which are implicated in obesity." (PMID 39596898, 2024). "Recent evidence in 9-year-old children with overweight/obesity followed up for 7 years until late adolescence concluded that increased physical activity (PA) decreased the risk of high fasting glucose, low insulin sensitivity, and secretion." (PMID 38441224, 2024). "Through these actions, BNP and ANP contribute to weight loss, improved insulin sensitivity, increased energy expenditure, and lowered risk of obesity and metabolic syndrome." (PMID 39335642, 2024). "There are medications associated with the development of obesity, known as obesogenic medications, which include mineralocorticoids, glucocorticoids, some antidiabetic drugs, insulin, and some antihypertensive medications, among many others." (PMID 38473918, 2024). "For instance, in humans, a rapid increase in BMI during the first year has been linked to lower insulin sensitivity, higher cholesterol, obesity, and increased visceral fat—all key factors that contribute to an elevated metabolic risk profile." (PMID 38337653, 2024). "Adherence to a MedDiet was associated with greater insulin sensitivity and decreased inflammatory markers in adults with overweight/obesity." (PMID 38978699, 2024). "These genes were involved in various biological pathways, such as lipid and energy metabolism, insulin secretion, adipogenesis, and neural development, adding insights into the underlying mechanism of obesity." (PMID 37620670, 2023). "Elevated levels of acetate are associated with obesity since acetate participates as a substrate in adipocyte and hepatic lipogenesis, as well as promoting secretion of ghrelin and insulin, leading to an increase in fat storage." (PMID 36977046, 2023). "Against this background, the primary aim of this cross-sectional study was to evaluate the association between adherence to MD and indices of IR, insulin sensitivity, and secretion in individuals with overweight or obesity." (PMID 37960178, 2023). "As discussed, metabolism is tightly regulated by the circadian clock, and energetic cues that alter the internal balance threaten physiological homeostasis, leading to increased risk for obesity, glucose and insulin imbalance, and cardiovascular disorders." (PMID 36834801, 2023).